KRAS (KRas proto-oncogene, GTPase)
Diseases named in the same sentence as KRAS in open-access papers (continued):
Sharing a sentence is not in itself a finding about the gene and the disease.
tumor (continued). "Further, we detected activating mutations in KRAS, ERBB2, RET, and CTNNB1, presumably conferring a new oncogenic driver in the respective tumor." (PMID 34201252, 2021). "We currently devise therapies for mCRC patients based on symptoms, primary tumor site, previous treatments, cancer stage, molecular evaluation (BRAF, KRAS or NRAS mutations and microsatellite instability), comorbidities, and treatment goals." (PMID 33809053, 2021). "In general, global efforts are made to design precision therapies to combat PDAC, including therapeutic targets to inhibit tumor-intrinsic pathways such as KRAS, PI3K, AKT, mTOR, JAK/STAT, SHH, NOTCH, and WNT signaling cascades." (PMID 34888306, 2021). "Activated CDC42-associated kinase 1 (ACK1), an activator of protein kinase B (AKT), is a promising target for KRAS-mutant tumor therapy, but the downstream ACK1 signaling remains poorly understood." (PMID 32530390, 2021). "This indicates in agreement with the GSEA data that vertical inhibition via blocking KRAS signaling in combination with controlling the feedback activation of the EGFR receptor phosphorylation via CET was critical to control this tumor." (PMID 34271981, 2021). "We observed that the MSKCC MSI-CRC cohort also included patients (64/97, 66%) with either a BRAF, NRAS, or KRAS mutation, whereas our MSI-CRC cohort was entirely composed of BRAF/NRAS/KRAS wild-type tumours." (PMID 34282766, 2021). "Co-dependent vulnerabilities and synthetic lethal partners are necessary for KRAS oncogenesis and tumour growth." (PMID 34944952, 2021). "KRAS activation is known to confer a clonal advantage to Apc-mutant ISCs, which leads to crypt fixation and in increased tumor growth." (PMID 34788095, 2021). "Pre-clinical studies revealed that KRAS inhibition through silencing with siRNAs or pharmaceutical inhibition of farnesylation of KRAS led to radiosensitization of tumor cells." (PMID 34537078, 2021). "Prominently, oncogenic KRAS alters glucose metabolism to support tumor growth, proliferation, and survival." (PMID 34680229, 2021). "Mutant KRAS is a common tumor driver and frequently confers resistance to anti-cancer treatments such as radiation." (PMID 33574444, 2021). "We cannot comment on putative differences of DEspR-inhibition between KRAS-mutant vs. wild-type PDAC tumor cells, however we note that > 80–90% of PDAC patients have KRAS mutations which are associated with worse prognosis." (PMID 33853558, 2021). "Single sample GSEA (ssGSEA) of human PDA tumours adjusted for tumour purity, confirmed differential signalling pathway engagement where OSMRlhigh tumours display increased KRAS pathway activity, PI3K-AKT-mTOR and IL6-JAK-STAT3 signalling." (PMID 34921158, 2021). "Using a quantitative multidimensional phenotype, we find that two tumor-associated mutations (PTEN loss and activated KRas overexpression) have distinct effects on behavior." (PMID 33986306, 2021). "Herein we present a large review of CRC and NSCLC tumor samples submitted for KRAS testing in a clinical certified laboratory." (PMID 33632153, 2021). "AMG 510 has shown in the preclinical studies to inhibit phosphorylation of extracellular signal-regulated kinase (ERK), a critical downstream effector of KRAS, producing a durable complete tumor regression in mice bearing KRAS p.G12C tumors." (PMID 34944853, 2021). "For the whole CRC population, univariate logistic regression analysis demonstrated that histology type, tumor location, degree of differentiation, and CEA and CA 19-9 levels were significantly associated with KRAS mutations." (PMID 34221952, 2021). "In this study, indeed, after KRAS extinction and complete tumor regression in all mice, about two thirds of them relapsed." (PMID 33777798, 2021).
tumor (continued). "TIB (tumor infiltrating B-cell) mediated responses, visualized by antibodies recognizing KRAS mutations, have been described in patients with pancreas adenocarcinoma (PDAC), highlighting their clinical utility in anti-tumor immune responses." (PMID 34335558, 2021). "Inhalation delivery resulted in significantly better survival of rats with the highly aggressive, EGFR mutant, H1975-derived lung tumors and the tumor burden of the moderately growing, KRAS mutant, A549-derived lung tumors." (PMID 33860729, 2021). "Previous research has indicated that the WT KRAS protein can either promote or inhibit tumor progression in KRAS mutant tumors in a context-dependent manner." (PMID 34573384, 2021). "Our results provide insight into the dynamics of tumour subclones over extended culture, as 40% of ten PDE with KRAS mutated cells showed a positive selection of these clones over time." (PMID 34572922, 2021). "KRas has been shown to be required for sustained tumorigenic growth in advanced PAC, with loss of KRas expression leading to tumor regression." (PMID 34680208, 2021). "The tumor harbored classical somatic changes of Wilms, namely canonical CTNNB1 and KRAS hotspot mutations and uniparental disomy of 11p." (PMID 34162837, 2021). "In a study in colon cancer mouse models, oncogenic KRAS was found to promote MDSC migration into the tumour microenvironment by repressing IRF2, leading to high expression of CXCL3." (PMID 34200676, 2021). "More importantly, the expression of KRAS and Myc was positively correlated with the circCD44 level in these tumor tissues." (PMID 34696797, 2021). "Genetically engineered mouse models of KRAS mutant cancer have confirmed that tumor regression can be achieved via KRAS extinction." (PMID 33674596, 2021). "Recent molecular studies of human tumor samples have demonstrated that somatic mutations in BAP1 and KRAS are among the most frequent mutations present in ICC." (PMID 34830866, 2021). "Small-molecule SOS1 inhibitor, BI-3406, interacts with the catalytic domain of SOS, resulting in interference with the interaction with KRAS and thereby restricting tumor cell proliferation in KRAS-mutant cancer, including G12 and G13." (PMID 34830757, 2021). "EOC is further classified into Type I and Type II tumours Low-grade tumours are type I tumours and carry mutations of BRAF, KRAS, and PTEN." (PMID 34987905, 2021). "Several evolutionary models, including parallel development and clonal selection have been proposed to explain the discordance rates of EGFR and KRAS between primary tumor and LCBM." (PMID 35201504, 2021). "The differences in tumor-intrinsic (co-existing genetic/epigenetic aberrations) and -extrinsic (tumor niche) factors likely explain the discrepancy in the therapeutic outcome of targeting KRAS in different cancer types." (PMID 34771644, 2021). "They showed that these KRAS knockout signatures were enriched in circulating tumor cells (CTCs) of PDAC relative to primary tumors." (PMID 34781949, 2021). "This study further provides genetic evidence that SOD1 is critical for KRAS mutant NSCLC tumor development and maintenance." (PMID 33859191, 2021). "Deltarasine has emerged as the most promising alternative impairing the KRAS location to endomembrane and, consequently, impairing tumour growth in CRC models with oncogenic KRAS." (PMID 34359657, 2021).
tumor (continued). "Next generation sequencing analysis of the postoperative tumor tissue revealed that KRAS copy number was increased and detected SMAD4, RNF43, and PREX2 mutations." (PMID 34888240, 2021). "ERK pathway suppression detected with NanoString gene expression was observed more commonly in those with BRAF-mutant tumours compared to those with KRAS-mutant tumours." (PMID 35582302, 2021). "In a previous study in lung-limited omCRC, we documented changes of KRAS status in metastatic formalin-fixed and paraffin-embedded (FFPE) tumor tissues compared to the primary ones (KRAS was mutated in primary tumor but not in subsequent metastases)." (PMID 34439390, 2021). "In preclinical studies, KRAS G12C direct inhibitors were noted to upregulate a pro-inflammatory tumor microenvironment and enhance anti-tumor T cell activity." (PMID 34845311, 2021). "Given its role in tumor pathogenesis, KRAS represents a viable target for therapeutics in human cancers." (PMID 33833221, 2021). "Currently, Phase II trials in combination with chemotherapy are undergoing in KRAS mutant CRC tumor types." (PMID 34944853, 2021). "KRAS mutations have been associated with lack of response for EGFR TKIs and due to the paucity of KRAS targeted therapies in the past, KRAS mutant tumor have been hard to treat with targeted therapies." (PMID 34257540, 2021). "The efficiency of anti-EGFR depends on the KRAS/BRAF mutation status, as it was demonstrated that BRAF-mutated tumours had reduced response rates to anti-EGFR, even though they were KRAS wild-type." (PMID 34945008, 2021). "KRAS proto-oncogene GTPase (KRAS) is a member of pro-tumor genes that always abnormally activated in diverse cancers." (PMID 33005174, 2020). "MEK inhibition induced tumor suppression in mice while reversing metabolic and immunosuppressive phenotypes, including chemokine production and gMDSC tumor recruitment in the chemoresistant KRAS-mutant tumors." (PMID 32634121, 2020). "According to the tumor tiuuse of CRC, another clinical study has confirmed that a positive correlation exists between KRAS mutation and HSP90 expression." (PMID 32922531, 2020). "In depth studies in murine models revealed that AMG-510 not only induced regressive disease due to inhibiting the KRAS signaling cascades, but additionally led to long-term anti-tumor T-cell responses." (PMID 32796566, 2020). "Among these key genes, KRAS is the best characterized tumor-related gene in PC with the highest frequency of KRAS point mutations located in codon 12 and with appearance even at early stages of PC carcinogenesis." (PMID 32338295, 2020). "To confirm these results, we reevaluated both tumor tissues using an alternative therascreen® KRAS test revealing the same result as the initial test." (PMID 33002027, 2020). "KRAS mutations are also associated with the PI3K pathway, which plays a fundamental role in the tumor–host interaction, enhancing tumor-induced angiogenesis and facilitating the establishment of metastatic colonies." (PMID 32471160, 2020). "Subsequent in vivo experiment showed that β-elemene in combination with cetuximab inhibited KRAS mutant tumor growth by inducing ferroptosis and suppressed cancer migration by regulating EMT." (PMID 32308771, 2020). "At present, KRAS is attracting more and more attention as a hot target in the field of anti-tumor drugs." (PMID 32210363, 2020). "For patients with CDX2 status available, 21% had a BRAF V600E mutation (BRAFmut), 41% a KRAS mutation (KRASmut), 8% were MSI high (MSI-H), and 38% double (KRAS and BRAF) wild-type tumor." (PMID 32117703, 2020). "In this context, the combined assessment of CD3, CD4 and CD8 IHC and tumour hypoxia by the Winters Metagene signature was found to be an independent predictor for survival when adjusted for clinical covariates, KRAS status and CRIS-B subtype." (PMID 32684627, 2020). "The KRAS signaling pathway, a well-known cancer-related signal transduction pathway, is involved in tumor metastasis and progression." (PMID 31978894, 2020).
tumor (continued). "Univariate analysis demonstrated radiologic tumour size, pathological stage (AJCC, 8th edition), nodal involvement, KRAS mutations and KRAS G12D mutation in ctDNA as considerable risk factors for RFS and OS." (PMID 31969677, 2020). "Our previous work has revealed that the expression of the dominant negative transcriptional regulator Id1 is a biomarker of poorer prognosis as it is associated with tumor progression, metastasis formation, and tumor-immunosuppression in KRAS-driven NSCLC." (PMID 33126649, 2020). "This polymorphism, harbored in the complementary site 6 (LCS-6) of the tumor suppressor miRNA let-7, alters the affinity between let-7 and its target oncogene KRAS, and consequently increasing cancer proliferation." (PMID 32987896, 2020). "Taken together, these findings suggest that the location of tumours on the left side can help predict the efficacy of anti-EGFR antibodies in mCRC patients with KRAS wt status." (PMID 33188279, 2020). "The BRAF gene, like KRAS, is one of the downstream EGFR oncogenic genes, and its somatic mutations activate the EGF receptor signaling in tumor cells." (PMID 33680376, 2020). "miR-193a-3p inhibits the formation, proliferation, and migration of tumor cells in the lung by directly binding to KRAS." (PMID 33510768, 2020). "A possible method is to analyze the plasma for driver mutations identified in the tumor, e.g., epidermal growth factor receptor (EGFR) exon 21 p.L858R or Kirsten rat sarcoma (KRAS) exon 2 p.G12D." (PMID 32117779, 2020). "Analysis of mut-KRAS needs to be tumor-informed or performed with NGS, whereas meth-HOXA9 can be analyzed directly in a simple, fast, and cheap ddPCR assay." (PMID 33322500, 2020). "The chemoresistant KRAS-mutant model showed gene expression and proteomic changes indicative of altered tumor cell metabolism." (PMID 32634121, 2020). "MSI status, KRAS, and BRAF mutation status were also characterized and compared between primary tumor tissues and tumor-derived organoids from 15 patients." (PMID 32290033, 2020). "KRAS mRNA level was significantly up-regulated in NSCLC tumor tissues compared with adjacent normal tissues in a total of 42 NSCLC patients." (PMID 33005174, 2020). "Of these 20 patients, 11 patients showed moderate reduction in sum of longest diameter of all tumor manifestations with a best change of −22.2% in a patient with NSCLC and KRAS mutation." (PMID 32436621, 2020). "Eight days after tumor implantation, mice were randomized and vaccinated with the KRAS mutant SLP–Lpx vaccine (G12D1–23–Lpx) and boosted after 1 week." (PMID 33298945, 2020). "In 5/17 (29%) cases, we observed the coincident BRAF, KRAS and NRAS mutations in cfDNA matched bone marrow tumor DNA." (PMID 32284750, 2020). "The repercussions of these distinct oncogenic properties are vast, should KRAS and NRAS mutations coexist within a heterogenous tumor." (PMID 32620824, 2020). "This can be interpreted that KRAS amplified tumor clones show a special affinity for lymphogenic metastasis." (PMID 32571252, 2020). "KRAS alterations associate with increased CD73, CD39, A2AR, and A2BR gene expression in CRC and NSCLC cell lines, which correlates with anti-PD-1 resistance in KRAS mutant tumor models." (PMID 32351498, 2020).
tumor (continued). "CRIS-C encompasses CIN tumours with wildtype KRAS status, MYC amplification and increased EGFR pathway activity." (PMID 32647253, 2020). "The oncogenic KRAS mutation allows for activation of many signaling pathways and transcription factors that promotes tumor cell proliferation and metastases; silencing of KRAS results in attenuated tumor growth." (PMID 33050151, 2020). "miRNAs let-7 family members generally promote differentiation during development and function as tumor suppressors in various cancers, and Let-7d regulation of KRAS has previously been shown." (PMID 32676506, 2020). "In accordance with this idea, we also combined the plasma ctDNA KRAS marker with routinely used tumor marker in gastrointestinal cancers-carcinoembryonic antigen (CEA)." (PMID 32867151, 2020). "An additional 65 studies contained relevant data for KRAS, NRAS, or BRAF mutation status and tumor sidedness but did not report data specific to the mCRC population or data for mutation status by tumor sidedness." (PMID 31856410, 2020). "There were previous studies where KRAS MASI elevated KRAS mRNA levels, increasing RAS activity and wild-type allele of KRAS has also been shown to play a pivotal role as a tumor suppressor." (PMID 32019606, 2020). "The organoid cultures well represented the morphologies and genetic landscape (i.e., KRAS and BRAF mutations and MSI status) of the primary tumor specimens." (PMID 32290033, 2020). "A recent study confirmed the synergistic action of KRAS and tumor suppressor gene mutations for development of IPMN in animal model and highlighted the role of Wnt/β-catenin pathway in KRAS-associated lesions." (PMID 32887490, 2020). "In a second experiment, we assessed the ability of the EF1-tTA to initiate tumor formation through upregulation of mutant KRAS." (PMID 31937792, 2020). "The second hit in the APC gene causes thousands of adenomatous polyps, and the accumulation of somatic mutations, including those in KRAS and BRAF, leads to tumor progression." (PMID 33060766, 2020). "The combination of GSK-J4 with doxorubicin in KRAS-mutant ATC achieved tumor-suppressive effects at a low dose." (PMID 32477122, 2020). "In three cases we were able to detect small KRAS amplified tumor cell populations in the primary tumor on additionally analyzed large scale slides of the primary tumor." (PMID 32571252, 2020). "The 21 women and 29 men with median age of 56.5 years (range 30–73) presented with T2 (10%), T3 (58%), or T4 (32%) disease, the majority (82%) with involved lymph nodes and tumor wild-type KRAS status (67% of the 39 analyzed cases)." (PMID 31893287, 2020). "The cultures presented a range of patient-specific morphologies and well represented the morphologies and genetic landscape (i.e., KRAS and BRAF mutations and MSI status) of primary tumor specimens." (PMID 32290033, 2020). "Other ongoing TCR therapies are against KRAS G12V + tumor (NCT03190941) and KRAS G12D + tumor (NCT03745326), both are at clinical trials phase I/II." (PMID 33042104, 2020). "This study showed the merit of KRAS-directed therapies in reducing in vitro proliferation and in vivo tumorigenic growth and revealed KRAS’ role in balancing proliferation and metastasis in tumor cells." (PMID 33117331, 2020). "In vivo, co-treatment with β-elemene and cetuximab inhibited KRAS mutant tumor growth and lymph nodes metastases." (PMID 32308771, 2020). "In contrast, when KRAS mutations are associated with STK11/LKB1 deficiency, the tumor landscape is cold and associated with reduced PD-L1 expression." (PMID 33276569, 2020). "Next, we examined the feasibility of detecting KRAS mutants using a tiny amount of resected tumor tissue." (PMID 32704002, 2020). "In accordance, the knockdown of mutant KRAS by Smakman and colleagues in a poorly immunogenic CRC mouse cell line caused an improvement in immune response and tumour regression." (PMID 33116132, 2020).